IL6 (interleukin 6)
Diseases named in the same sentence as IL6 in open-access papers (continued):
Sharing a sentence is not in itself a finding about the gene and the disease.
viral infection (continued). "Despite the IL-6 role in diseases related to virus infection like hepatitis and HIV, the lower levels detected in the infectious diseases group might be explained by some participants undergoing anti-retroviral therapy." (PMID 39328992, 2024). "Additionally, the elevation in body temperature suggests an inflammatory response triggered by the production of pyrogenic cytokines such as IL-6 in response to viral infection to mitigate the ensuing disease." (PMID 39094475, 2024). "For instance, electrochemical nanobiosensors could be integrated into Lung-on-Chip models to monitor cytokines like IL-6 or TNF-α during a viral infection." (PMID 39589620, 2024). "Additionally, we found that secondary viral infection caused a significant upregulation of TNF-α, IL-6, and IFN-β in lung and brain tissues compared to bacterial or viral infections alone." (PMID 40303164, 2024). "During the preliminary levels of viral infection in airway epithelial cells, regulated and programmed cell death responses known as pyroptosis take place, releasing seasoned-inflammatory cytokines and chemokines such as IL-6, IFNγ, MCP1, and IP-10." (PMID 38694803, 2024). "The production of inflammatory cytokines in the target tissue is part of the innate immune response to viral infection, the levels of cytokines (interleukin (IL)-6, IL-8, Tumor necrosis factor (TNF)-α, and interferon (IFN)-α) in the jejunum and colon of piglets were detected using the qRT-PCR." (PMID 38349151, 2024). "As such, IL-6 plays a protective role in different viral infections." (PMID 38251210, 2024). "Furthermore, IL-6 together with IL-15 regulates the cytotoxic function of the CD8+ T cells as the main adaptive immune cells in viral infections." (PMID 39062668, 2024). "IL-6, produced in response to tissue damage and infections and during certain viral infections, may promote virus survival and/or exacerbation of clinical disease." (PMID 38707035, 2024). "In addition to cytokine release, including upregulation of the pro-thrombotic cytokine IL-6, we show that viral infection also triggered the release of Factor VIII, a component of the intrinsic coagulation pathway." (PMID 38576426, 2024). "This viral infection triggers an exaggerated immune response, often referred to as a cytokine storm, characterized by the excessive release of pro-inflammatory cytokines such as IL-6, IL-1β, and TNF-α." (PMID 39272485, 2024). "Since in patients with viral infection it could exert an anti-inflammatory effect by inhibiting proinflammatory cytokines, such as IL-6 and TNF-α." (PMID 39460768, 2024). "In addition, the multifunctional cytokine (IL-6) was included as an independent variable in this study, as it plays an essential role in periodontal disease and viral infection." (PMID 39917640, 2024). "Cortisol production is strongly induced when blood IL-6 levels are high, and the suppressive effect of HC on IL-6 levels during viral infection in this study may have reduced cortisol levels." (PMID 38957464, 2024). "Among the most prominent elevated cytokines we observed IL-6, a pleiotropic cytokine involved in host defense; its elevation may be a part of tissue response to viral infection and SARS-CoV-2-induced tissue injury." (PMID 39497823, 2024). "In addition, IL-6 triggers pro-inflammatory effects, such as monocyte recruitment to the site of inflammation due to viral infection." (PMID 38847223, 2024). "However, during viral infections such as COVID-19, IL-6 levels can rise dramatically, sometimes exceeding 100 pg/mL, especially in severe cases." (PMID 39589620, 2024). "However, a role for IL6 in cardiac dysfunction, including propensity to arrhythmias, is not limited to systemic inflammatory diseases or viral infections." (PMID 39596280, 2024). "IL-6 has been reported to limit viral replication in the early stages of viral infection." (PMID 38051045, 2023).
viral infection (continued). "Environmental triggers such as viral infection or danger signals are recognized by monocytes, resulting in the activation of inflammatory pathways and over-production of cytokines, including IL-1β, IL-6, IL-18, and TNF." (PMID 38124139, 2023). "Moreover, HPV vaccines have been associated with increased levels of cytokines (IL-2, IL-6, IL-1α, and IL-1β) and with the induction of IFN-γ-producing CD4+ and CD8+ T-lymphocytes, cytotoxic cells that clear viral infections." (PMID 38068369, 2023). "The host immune targets such as TLR7, IRF7, IRF5, and IL6, which are involved in the immune response against viral infections, and the sex-specific targets such as AR and ESSR were taken to investigate any possible link with the SARS-CoV-2 host receptors ACE2 and TMPRSS2." (PMID 36992366, 2023). "Moreover, the administration of VO extract reduced the release of inflammatory cytokines (TNF-α, IL-1β and IL-6) triggered by viral infection to a level comparable to that of the Control group." (PMID 37108306, 2023). "However, the role of IFN-γ on IL-6 production in the bronchial epithelial cells in response to viral infection remains to be investigated." (PMID 38030681, 2023). "Various cell types are involved in IL-6 production in response to viral infection." (PMID 38030681, 2023). "Indeed, we did observe elevated levels of the chemoattractant CXCL10 and pro-inflammatory IL-6, both essential cytokines for initiating migration of several innate and adaptive immune cells and responding to viral infection, respectively." (PMID 37724882, 2023). "Indeed, in addition to the activity against viral infection, both GlcNAc and GlcNAc-NPs also decreased the expression level of IL-6, IL-8 and TNF-α mediators during IAV infection, indicating that it also possesses an anti-inflammatory effect." (PMID 36982205, 2023). "First, there are biological differences in the expression of ACE2 I transmembrane protease serine 2 (TMPRSS2) receptors between males and females, and immunological differences; lower production of pro-inflammatory interleukin-6 (IL-6) due to viral infection in women." (PMID 37048610, 2023). "In recent years, studies have shown that viral infections such as HHV-8, HIV, and EBV can cause activation of the autoimmune system, resulting in the release of cytokines such as IL-6, and hyperproliferation of B lymphocytes and plasma cells in lymphoid tissues." (PMID 38062501, 2023). "The reason for the vascular leakage in DHF patients is the massive release of pro-inflammatory cytokines and chemokines upon viral infection, such as interleukin-6 (IL-6), IL-8, IL-1β, vascular endothelial growth factor, and tumor necrosis factor-α (TNF-α), leading to endothelial cell damage." (PMID 37112864, 2023). "To explore the effect of SPJ treatment on cytokine expression, we used real‐time PCR and observed that viral infection led to increased expression of cytokines and chemokines, including IL‐6, IL‐1β, TNF‐α, IL‐10, IFN‐α, IFN‐β, and IFN‐γ, as well as CXCL‐2, CXCL‐10, CCL‐2, CCL‐3, and CCL‐5." (PMID 37544014, 2023). "In addition, a high level of IL-6, which represents the key cytokine in the event of viral infection, activates the intravascular coagulation cascade, which is also associated with more severe clinical manifestations of SARS-CoV-2 infection." (PMID 36675526, 2023). "The analysis confirms the previously data concerning the important involvement of IL-6 in the inflammatory response to a virus infection but give also new insights on the mechanisms governing the IL-18 production and regulation in the case of human Sars-CoV2 infection." (PMID 36385417, 2023). "Interleukin-6 is the cytokine involved in severe forms of viral infection and telogen effluvium." (PMID 37511952, 2023). "Interestingly, several investigations have demonstrated the protective role of IL-6 during viral infections." (PMID 38053527, 2023).
viral infection (continued). "Furthermore, viral infection increased the mRNA expression of cytokines (Il6, Tnf), chemokines (Cxcl10, Ccl2), and interferon-responsive genes (Ifnb1, Ifit3, Irf7, Gbp5 and Isg15)." (PMID 37081549, 2023). "Moreover, the serum IL-1β level was extremely low during the entire course of virus infection in patients with severe outcomes, whereas IL-6 appeared to maintain higher levels at baseline and gradually increase after infection." (PMID 37035158, 2023). "Interleukin-6 (IL-6) upregulation has been observed during viral infections in both mice and humans, implying that it may influence the disease outcome significantly." (PMID 38053527, 2023). "The cytokine storm hypothesis suggests that the uncontrolled release of pro-inflammatory cytokines following viral infection, particularly IL-6, is crucial in ANEC pathogenesis." (PMID 38178890, 2023). "The cytokine analysis results showed that a PRV infection could increase the levels of TNF-α, IFN-γ and IL-6 and reduce the level of IL-4 to regulate the body’s immune response to a virus infection." (PMID 37508153, 2023). "IL-6 and IL-12 are secreted by macrophages and dendritic cells in response to virus infection." (PMID 36077417, 2022). "It has been reported that serum levels of IL-6 and IL-10 are increased in severe viral infection." (PMID 36406394, 2022). "Many inflammatory disorders, including viral infections, has been found to be regulated by IL-6." (PMID 36506506, 2022). "Inflammatory factors related to viral infection, such as IL-6, IL-8, and granulocyte colony-stimulating factor, could stimulate neutrophil production." (PMID 35890037, 2022). "Our findings demonstrated that DSV blocks the interaction of viral S protein with ACE 2, thereby downregulating the virus infection-induced pro-inflammatory cytokines (IL-6), (IL-1β), and (TNF-α) which are highly elevated instigating the innate anti-viral response." (PMID 36386162, 2022). "As it happens with other viral infections, the innate immune response is the first barrier in the fight against the virus, secreting inflammatory cytokines such as interleukin 1 (IL-1), interleukin 6 (IL-6) and type I interferon (IFNs), and subsequently activating the adaptive immune response." (PMID 35831294, 2022). "Similarly, BM CXCL12-abundant reticular (CAR) cells secrete IL-6 in response to IFN-γ by CD8 T cells during viral infection, and IL-6 in turn favors HSPCs differentiation toward myeloid lineages." (PMID 36148240, 2022). "According to a study on influenza virus A, the levels of IL-6 in the site of initial virus infection were increased persistently for 6 days, this may be related the level of IL-6 in HMPV-positive patients was lower than that of IVA-positive patients." (PMID 36496397, 2022). "IL-1β and IL-6, pro-inflammatory cytokines having critical roles in infection and inflammation, have been found to be associated with severe lung injury during influenza A (H1N1) virus infection." (PMID 36106521, 2022). "Elevated levels of IL-6 are often identified during severe viral infections." (PMID 35512020, 2022). "Additionally, it is noteworthy that the infection in the respiratory system intriguingly downregulated the expression of interferon-beta (IFN-β), interleukin 21 (IL-21), and IL-6 in the bone tissue, which are vital for the clearance of virus infection." (PMID 35534483, 2022). "Others link this cytokine to exacerbation of the viral disease, supporting the hypothesis that up-regulation of IL-6 during viral infections may promote virus survival and clinical disease exacerbation." (PMID 36615820, 2022). "Notably, it was shown that the induction of the synthesis of cytokines, TNFα, IFNβ and IL6 in macrophages by viral infection was RKIP dependent." (PMID 35892864, 2022). "Viral infection is able to upregulate various senescence markers, including SA-b-gal, p16, p21, and pro-inflammatory senescence-associated secretory phenotypes (SASP) molecules IL-6 and IL-8." (PMID 36139488, 2022).
viral infection (continued). "Since PCLS could respond to fibrosis cocktails and induce Il6 and Col1a1, we concluded that viral infections, such as SARS-CoV-2, strongly suppress fibrosis." (PMID 36405683, 2022). "Overall, procalcitonin may not be a reliable indicator of bacterial infection in severe viral diseases with raised IL-6 levels." (PMID 35531376, 2022). "IL-1, IL-6 and TNFα are three main pro-inflammatory cytokines that are produced by endothelial and epithelial cells, macrophages and mast cells during innate immune response against viral infection." (PMID 35500008, 2022). "It has been suggested that smoking may affect interleukin 6 levels and influence inflammation and viral disease severity." (PMID 36504971, 2022). "IL-6 is an important cytokine in host responses against viral infection." (PMID 35337002, 2022). "The JAK2 and IL6/JAK2/STAT3 signaling pathways are therapeutic targets for treating excessive inflammatory response to virus infection, where PIK3CB, the target of miRNA−34a participated in TCR−mediated NF−κB signaling after binding to B7 ligand on antigen presenting cells (APC)." (PMID 36298658, 2022). "Through induction of IFN-gamma IL-18 primes mononuclear phagocytes for TNF-alpha-induced IL-6 expression, which might be particularly relevant during the later stages of viral infection." (PMID 35860660, 2022). "Among these cytokines, type-1 interferons, which include IFN-α, IFN-ß and IL-6, are promptly and transiently produced to contribute to the host’s antiviral defense; thus, the expression of these genes is also an indicator of the extent of the viral infection." (PMID 36560517, 2022). "During viral infections, IL-6 and IL-1β can facilitate inflammation in the alveoli and bronchi." (PMID 33995078, 2021). "It has been proved that viral infection induces IL-6 production through TNF-α." (PMID 37287491, 2021). "When viral infections are considered, good IL-6 producers may benefit at the front line of infection (e.g. in the common cold) but not when the disease goes wrong, high IL-6 individuals are more susceptible to acute respiratory distress syndrome." (PMID 34149697, 2021). "As a stable indicator, the changes in IL-6 levels could indicate the inflammatory conditions during a viral infection." (PMID 33746945, 2021). "PCT viral infection may be released under the action of proinflammatory mediators such as IL-6, TNF release or the like, which leads to elevated levels of peripheral blood." (PMID 33775266, 2021). "In addition, BAL IL-6 and IL-17 also trended toward upregulation in patients with mixed bacterial-viral infections." (PMID 34602860, 2021). "Importantly, IL-6 promotes differentiation of naïve CD8 T cell into a unique population of effector CD8+ T cells for antagonizing the viral infection." (PMID 34202218, 2021). "Doxycycline may also exert anti-inflammatory effect in patients with viral infection by inhibiting pro-inflammatory cytokines, including IL-6 and tumor necrosis factor (TNF)-α." (PMID 34020659, 2021). "IL-6 gene expression was significantly higher only after virus infection." (PMID 34200003, 2021). "Many of these miRNA pathway targets related to immunological outcomes such as leukocyte and monocyte migration/chemotaxis, cell adhesion molecules, toll-like receptor signaling, cytokine receptor signaling, viral infection response, and negative regulation of IL-6 production." (PMID 35004828, 2021). "As a cytokine critical to mediate inflammation, IL-6 has pleiotropic activity and may play an opposing role in the immune response to different viral infections." (PMID 34764867, 2021). "Moreover, the sustained activation of multiple cytokine pathways by IL-6 plays a major role in the development of cytokine storm and in the pathogenesis of virus infection." (PMID 35062229, 2021).
viral infection (continued). "IL-6 is a cytokine of pleiotropic activity, but during viral infections, IL-6 is considered one of the most important cytokines for its regulation of T-cell response, prevention of viral-induced apoptosis of lung epithelial cells, regulation of IgG isotype switching, and other functions." (PMID 34484241, 2021). "IL-6, a proinflammatory cytokine, is essential for escalating the cell response to control persistent viral infection, and expression of IL-10, an important anti-inflammatory cytokine, is significantly elevated in SFTS patients, especially in patients with fatal disease." (PMID 34484214, 2021). "Moreover, IL-6 plays an important role in controlling viral infections such as influenza A, SARS-CoV-1, and herpesvirus." (PMID 34884178, 2021). "The inability to promptly defeat a viral infection can elicit a cytokine storm, in which pro-inflammatory molecules including Interleukin-1β (IL-1β), Interleukin-6 (IL-6), and Tumor necrosis factor (TNF-α) are released in pathogenic concentrations causing systemic hyperinflammation." (PMID 33679437, 2021). "Upregulated expression of cytokines, chemokines and growth factors was commonly observed in patients and animals with lymphopenia induced by viral infection, including IL-2, IL-6, IL-12, IL-18, IL-1β, IFN-γ, CCL2/MCP-1, CXCL1, CXCL8/IL-8, CCL3/MIP-1-α, CCL7/MCP-3, CXCL10/IP-10 and CXCL9/MIG." (PMID 34578457, 2021). "It has been shown that these viral infections could lead to systemic inflammation with a high level of IL-6, IL-1β, and TNFα." (PMID 33607952, 2021). "Virus infection of antigen presenting cells, such as dendritic cells, macrophages, and other cell types including endothelial cells, result in activation of biochemical signals, which lead to secretion of a battery of cytokines that include IL1β and IL-6." (PMID 34367726, 2021). "Production of IL-6 might be detrimental during viral infections, promoting virus survival and/or exacerbation of clinical disease." (PMID 34359931, 2021). "In this study, excessive levels of the IL-6 cytokine were observed due to viral infection." (PMID 35087503, 2021). "Even though there was no microbiologically-confirmed bacterial coinfection in the viral group of the current study, some patients with primary viral infection displayed relatively high IL-6 levels, which could indicate an undetected bacterial superinfection." (PMID 33673270, 2021). "Furthermore, it has been reported that IL-6 is an essential factor for the survival of mice with a viral infection." (PMID 32354030, 2020). "In addition to modulating the host immune response, IL-6 has been involved in the progression of various viral diseases." (PMID 33244370, 2020). "With this regard, TCZ is a good therapeutic option for disrupting the IL-6 amplifier, an IL-6-mediated hyper-inflammatory mechanism that can be triggered by innate immune signaling upon viral infection together with Ang II-AT1R-mediated signaling due to the reduction of Ang II-quencher ACE2." (PMID 33014208, 2020). "The present study investigates the correlation of elevated CF mt-DNA levels with IL-6 and viral load in viral infections i.e. HIV, HBV and HCV and the possibility of a potential role for CF mt-DNA as a marker for disease severity and disease progression in viral infections." (PMID 32704253, 2020). "Our observation of significantly increased IL-6 release from neonatal DCs during Poly(I:C) induced maturation, which mimics a viral infection, might have important modulatory functions during the polarization of naive T cells in early life." (PMID 31711888, 2020). "Indeed, the results of experimental viral infections in vitro and in vivo confirm that the main sources of IL-6 in the CNS are astrocytes." (PMID 32294697, 2020).